HPSE (heparanase)
Diseases named in the same sentence as HPSE in open-access papers (continued):
Sharing a sentence is not in itself a finding about the gene and the disease.
diabetic nephropathy (continued). "Progress in the field expanded the scope of heparanase function and its significance in tumor progression and other pathologies such as inflammatory bowel disease and diabetic nephropathy." (PMID 23908791, 2011). "Heparanase activity was increased in the urine of diabetic patients and reduction of HS moieties in the glomeruli of patients with overt diabetic nephropathy in type II diabetes was correlated with heparanase upregulation." (PMID 19695080, 2009). "In addition, elevated levels of heparanase have been identified in various human proteinuric glomerular diseases, including diabetic nephropathy and different forms of glomerulonephritis." (PMID 40495439, 2025). "Although in early diabetic nephropathy inhibition of HPSE-1 activity has been shown to protect the endothelial glycocalyx and to prevent development of proteinuria, we could not demonstrate this effect in the present study." (PMID 38600065, 2024). "Furthermore, a systemic HPSE knock-out prevented mice from the development of proteinuria upon inducing experimental diabetic nephropathy." (PMID 33951113, 2021). "In DM1, increased expression of heparanase and possibly sulfatases may be involved in modulation of HS, as has been documented for diabetic nephropathy." (PMID 33472641, 2021). "Moreover, HPSE is crucial for the development of glomerulonephritis and diabetic nephropathy as HPSE knock-out mice disease models showed significantly reduced proteinuria, which is another feature of dengue-associated plasma leakage." (PMID 34987504, 2021). "Notably, a role for heparanase was identified in several proteinuric nephropathies, mainly in the pathogenesis of diabetic nephropathy and in a model of septic AKI." (PMID 28388547, 2017). "We recently showed that heparanase is essential for the development of experimental diabetic nephropathy and glomerulonephritis, and hypothesize that heparanase expression is regulated by eNOS." (PMID 27505185, 2016). "This increased heparanase expression may explain a reduced thickness of the glomerular endothelial glycocalyx in (experimental) glomerular diseases, like diabetic nephropathy and adriamycin nephropathy." (PMID 27505185, 2016). "Heparanase upregulation has been reported in cancer, diabetic nephropathy, and inflammation." (PMID 25513953, 2014). "Except for AGE-RAGE, heparanase is another target gene of the diabetic nephropathy mediators albumin and AGE, which was proved by experimental evidence to play a key role in AGEs-induced macrophage migration associated with inflammation in diabetic vascular complication." (PMID 25391642, 2014). "This suggests that heparanase is continuously activated by immunocyte derived cathepsin L despite treatment with sepiapterin, which could potentially explain that restoration of glycocalyx coverage by sepiapterin in diabetic nephropathy was only partial." (PMID 28103268, 2017). "ETAR antagonism increased the endothelial glycocalyx, decreased glomerular heparanase and reduced ACR in mice with diabetic nephropathy." (PMID 38271614, 2024). "Additionally, since HPSE expression correlates inversely with HS content in the glomerular basement membrane, it has been suggested that the degradation of the glomerular HS by HPSE plays a role in the development of proteinuria particularly in diabetic nephropathy." (PMID 26040666, 2015). "In fact, diabetic heparanase null mice failed to develop diabetic nephropathy in response to streptozotocin." (PMID 29226146, 2017). "While sepiapterin successfully increased the modulating potential of NO in this model of diabetic nephropathy, immunocytes were not affected, hence glomerular heparanase and cathepsin L were not reduced and glycocalyx properties not restored." (PMID 28103268, 2017).
diabetic nephropathy (continued). "Indeed, immunohistochemical analysis showed that heparanase is expressed in tubular epithelial cells but not in glomeruli of normal kidney, while its expression is upregulated in the glomeruli and tubular epithelial cells in kidneys with diabetic nephropathy." (PMID 21364956, 2011).
COVID-19 (30 papers, 2020 to 2024). A disease caused by infection with severe acute respiratory syndrome coronavirus 2. "Plasma heparanase activity is significantly increased in the circulation in patients with COVID-19 and is associated with disease severity, being highest in ICU patients receiving mechanical ventilation." (PMID 37111341, 2023). "Here, we report increased HPSE activity and HS levels in plasma of COVID-19 patients, which were also associated with severity of the disease." (PMID 33123154, 2020). "A study of 48 hospitalized COVID-19 patients found evidence of endothelial barrier destruction and increased plasma heparanase associated with disease severity." (PMID 33375371, 2020). "In summary, this cross-sectional study shows that HPSE activity and HS levels are significantly elevated in plasma of COVID-19 patients, which is associated with the severity of COVID-19." (PMID 33123154, 2020). "The activity of heparanase has been associated with disease severity in COVID-19 patients, and LMWHs could reduce its activity." (PMID 38673677, 2024). "Determine whether heparanase and heparan sulfate fragments, biomarkers of endothelial function, can assist in the risk stratification and clinical management of critically ill COVID-19 patients admitted to the intensive care unit." (PMID 36142913, 2022). "A small study suggests that heparanase activity is unchanged in COVID-19, despite evidence of glycocalyx injury, while a recent, cross-sectional report indicates that heparanase activity strongly associates with COVID-19 severity." (PMID 34314391, 2021). "Notably, we recently also showed a possible role of HPSE in mediating endothelial glycocalyx degradation in severe coronavirus disease (COVID-19) associated lung edema." (PMID 34987504, 2021). "Heparanase is increased in COVID-19 patients and is related to its pathogenicity through factor X activation." (PMID 38673677, 2024). "In fact, our work confirms and extends this data by showing a clear potential of heparanase activity and heparan sulfate plasma levels as promising biomarkers for the prediction of disease severity and outcome of COVID-19 patients admitted to the ICU." (PMID 36142913, 2022). "Heparanase activity and serum levels of both heparanase and heparan sulfate were measured on day one (day of diagnosis) and day three in patients with COVID-19." (PMID 36142913, 2022). "In conclusion, our translational study indicates that HPSE is a putative mediator of endothelial glycocalyx damage in COVID-19." (PMID 35757776, 2022). "Elevated plasma heparanase activity in COVID-19 patients can lead to the bradykinin pathway activation by the cleaving of HS and can subsequently trigger the inflammatory response and vascular leakage." (PMID 35741101, 2022). "In conclusion, in this study, we showed that heparanase activity increased in patients with severe ARDS on both days in COVID-19 patients." (PMID 36142913, 2022). "The finding that HPSE activity in healthy individuals and COVID-19 patients was inversely correlated with HS concentration suggests that a minimum amount of HPSE is required before systemic eGC degradation begins." (PMID 35757776, 2022). "The level and activity of heparanase, the exclusive mammalian HS-degrading enzyme, are elevated in COVID-19 patients." (PMID 35741101, 2022). "Here we show that HPSE, the only enzyme in mammals that degrades HS chains from HS proteoglycans of the glycocalyx, plays a key role in mediating eGC damage in COVID-19." (PMID 35757776, 2022). "Another intriguing potential therapeutic role of heparin in COVID-19 seems to be the inhibition of heparanase, an endothelial glycocalyx-degrading enzyme that contributes to vascular leakage and inflammation." (PMID 35683485, 2022). "Two recent studies have shown the implication of heparanase in glycocalyx shedding in adults with COVID-19." (PMID 35347344, 2022). "Heparanase is increased in COVID-19 and contributes to endothelial dysfunction with increased leakage." (PMID 34986821, 2022).
COVID-19 (continued). "Heparanase activity and heparan sulfate levels correlate with COVID-19 disease severity and outcome." (PMID 36142913, 2022). "The aim of this translational proof-of-concept study was to investigate the role of HPSE in COVID-19-induced eGC damage." (PMID 35757776, 2022). "Levels of heparanase, known to degrade the endothelial glycocalyx, were found to be considerably higher in COVID-19 patients than healthy controls and the levels of heparanase activity are linked to the severity of COVID-19 disease." (PMID 34532323, 2021). "In a related study, Buijsers and colleagues found that heparanase activity and heparan sulfate levels were elevated in hospitalized COVID-19 patients compared with those in HC." (PMID 34792686, 2021). "The proposed mechanisms to explain heparanase involvement in the severe forms and worsened outcomes of COVID-19 include its well-established roles in the degradation of the endothelial glycocalyx and the activation of inflammatory responses." (PMID 34207476, 2021). "In this commentary, we will refer to potential evidences about the involvement of HSPGs and heparanase in COVID-19-induced coagulopathy, infectivity of SARS-CoV-2 and viral cell release." (PMID 34132790, 2021). "Of particular relevance are recent studies on the presumed involvement of heparanase and heparan sulfate in the pathogenesis of COVID-19." (PMID 34199150, 2021). "In line with the increased HPSE activity, HS plasma levels were also significantly elevated in COVID-19 patients compared to healthy controls." (PMID 33123154, 2020). "Measurement of plasma HPSE activity levels in COVID-19 patients and healthy controls revealed that HPSE activity was significantly elevated in COVID-19 patients compared to healthy controls." (PMID 33123154, 2020). "Plasma heparanase activity and heparan sulfate levels were significantly elevated in COVID-19 patients." (PMID 33123154, 2020). "One important, currently overlooked characteristic of heparin/LMWH in the pathogenesis of COVID-19 is the inhibitory effect on heparanase (HPSE)." (PMID 32853989, 2020). "The ultimate shared pathway of eGC damage, particularly in bacterial sepsis and COVID-19, seems to involve the activation and release of heparanase (HPSE), a heparan sulphate (HS)-degrading enzyme that is unique to mammals and breaks down HS chains from HS proteoglycans found in the glycocalyx." (PMID 38598083, 2024). "Histone and heparanase levels could explain interindividual sensitivities to heparin in COVID-19 patients." (PMID 38673677, 2024). "Furthermore, another study showed a significantly higher heparanase activity and increased levels of heparan sulfate in plasma of COVID-19 patients." (PMID 36142913, 2022). "Another study found that plasma heparanase activity and plasma heparan concentration were higher in COVID-19 patients compared to healthy controls, and that heparanase activity was significantly higher in ventilated ICU COVID patients vs. non-ICU COVID patients." (PMID 35872762, 2022). "The aPTT was significantly prolonged in COVID-19 and correlated positively with HPSE activity (R = 0.58, P < 0.001), suggesting that the true HPSE activity in severely ill COVID-19 patients could be even higher than the values actually measured." (PMID 35757776, 2022). "Therefore, the aim of this study was to investigate the relationship between heparanase activity and heparan sulfate fragment formation and outcome in COVID-19 patients and to determine the prognostic value of these potential new biomarkers in ARDS." (PMID 36142913, 2022). "Furthermore, heparanase activity and heparan sulfate levels correlate with COVID-19 disease severity and outcome." (PMID 36142913, 2022). "Indeed, Buijsers and colleagues demonstrated that heparanase activity and heparan sulfate levels are significantly increased in the plasma of COVID-19 patients, which is related to the severity of the disease." (PMID 36142913, 2022).
COVID-19 (continued). "However, the paradoxical decrease in HPSE activity in the COVID-19 patients with the highest HS concentrations certainly complicates any interpretation of HPSE activity in plasma samples." (PMID 35757776, 2022). "Consequently, in this work, the role of heparanase and heparan sulfate in COVID-19 patients in relation to the severity of ARDS was investigated." (PMID 36142913, 2022). "Based on these results, there is now good evidence that heparanase activity may play a role in endothelial dysfunction and ARDS associated with COVID-19 and may be a potential biomarker to predict outcome in COVID-19 patients in the ICU." (PMID 36142913, 2022). "However, the involvement of heparanase in COVID-19-induced glycocalyx damage has yet to be formally demonstrated and needs further study." (PMID 33058027, 2021). "Besides heparin as a blood thinner to promote anticoagulation via binding to anti-thrombin III, heparin is also beneficial in COVID-19 by preventing endothelial leakage (inhibition of heparanase) and blocking leukocyte infiltration." (PMID 34869231, 2021). "This suggests that increased HPSE activity may play a role in the severe clinical manifestations of COVID-19, including ARDS, and AKI." (PMID 32853989, 2020). "We hypothesize that heparanase contributes to the pathogenesis of COVID-19, and that heparanase may be inhibited by LMWH." (PMID 33123154, 2020). "Notably, heparins and low molecular weight heparins (LMWH) that have been suggested to be beneficial for COVID-19 patients, are potent inhibitors of HPSE activity." (PMID 33123154, 2020). "Moreover, HPSE activity remained high in COVID-19 patients in ICU, all of whom received prophylactic LMWH as part of standard ICU treatment regimen." (PMID 33123154, 2020). "Taken together, we hypothesize that increased HPSE activity is one of the driving forces in severe COVID-19 manifestations and that HPSE may be inhibited by the use of LMWH in COVID-19." (PMID 33123154, 2020). "The keywords “glycocalyx COVID-19”, “syndecan coronavirus”, hyaluronic acid COVID-19”, “heparanase COVID-19”, and “PBR COVID-19” were searched in databases such as PubMed, the WHO Global Health research database on COVID-19, and Japan Medical Abstracts Society." (PMID 33352699, 2020). "Targeting of HPSE activity could be beneficial for the clinical outcome of COVID-19 patients, since it is well established that increased HPSE activity compromises the endothelial glycocalyx and contributes to a pro-inflammatory cytokine milieu." (PMID 33123154, 2020). "Therefore, low molecular weight heparin may inhibit the formation of slow kinin by inhibiting heparanase activity and binding to high molecular weight kininogen, thereby reducing local inflammation and vascular leakage of COVID-19." (PMID 37765064, 2023). "Therefore, it is hypothesized that increased heparanase activity may be one of the driving forces in severe COVID-19 manifestations." (PMID 36142913, 2022). "Notably, in a recent preprint we showed increased plasma HPSE activity in COVID-19 patients." (PMID 32853989, 2020). "Eight genes associated with platelet activation and pro-thrombosis were upregulated in COVID-19 patients: MPIG6B, HBB, HPSE, CD40LG, STXBP3, CLEC1B, TFPI and GNAS." (PMID 35477940, 2022). "The inhibition of heparanase by a non-anticoagulant heparin fragment prevented glycocalyx destruction in response to COVID-19 serum treatment." (PMID 38673677, 2024). "Heparin-mediated inhibition of heparanase activity was recently shown to limit SARS-CoV-2 infectivity in vitro, and when inhaled may similarly limit viral spread and the development of COVID-19." (PMID 37111341, 2023). "Competitive inhibition of heparanase by the nonanticoagulant heparin fragment NAH completely prevented the decline in eGC thickness in response to COVID-19 serum." (PMID 35757776, 2022).
COVID-19 (continued). "One of the potential systems that may play a crucial role in the exaggerated coagulation characterizing COVID-19 is the Heparan sulfate proteoglycan (HSPG) and Heparanase system." (PMID 34132790, 2021). "LMWH is as an inhibitor of the endothelial glycocalyx-degrading enzyme heparanase, which is well known to exacerbate vascular leakage and inflammation, and may be involved in the development of ARDS in COVID-19." (PMID 33375371, 2020). "Since there is no other clinically applied heparanase inhibitor currently available, therapeutic treatment of COVID-19 patients with low molecular weight heparins should be explored." (PMID 33123154, 2020). "Considering the fact that no specific clinically approved heparanase inhibitors are currently available, prospective studies evaluating the clinical outcome of COVID-19 patients treated with therapeutic doses of LMWH are urgently needed." (PMID 33123154, 2020). "Interestingly, separate analysis of the two groups revealed contrasting regression slopes, suggesting that excessive generation of HS fragments in severe COVID-19 (which was not present in controls) may have partially blocked HPSE activity in COVID-19 patients." (PMID 35757776, 2022). "Additional heparanase inhibitors are under clinical and basic science research, like SST0001, but NCT identifier search revealed no studies for these compounds in COVID-19 patients." (PMID 34132790, 2021). "We next compared activity levels of GAG-degrading enzymes in non-ICU– and ICU-admitted patients with COVID-19 and observed that ICU-admitted patients show elevated circulating hyaluronidase and heparanase, as well as a trend toward increase in chondroitinase activity." (PMID 34314391, 2021).